SMURF2 (SMAD specific E3 ubiquitin protein ligase 2)
Diseases named in the same sentence as SMURF2 in open-access papers (continued):
Sharing a sentence is not in itself a finding about the gene and the disease.
tumor (continued). "By contrast, Smurf2 has also been suggested to promote the proliferation of breast cancer tumor cells, tumor formation and metastasis in xenograft models." (PMID 28423498, 2017). "The median of the Smurf2 staining scores in TNBCs was 2 (25%-50% of tumor cells were Smurf2-positive), while that in ER+/PR + cancers was 3 (50%-75% Smurf2-positive)." (PMID 24485087, 2014). "Several lines of evidence implicate that Smurf2 and its interacting partners or substrates are involved in cell invasion and tumour metastasis." (PMID 25191523, 2014). "Increased susceptibility of Smurf2-null mice to spontaneous tumorigenesis has provided key evidence for the tumor suppressive actions of Smurf2." (PMID 24485087, 2014). "The activity of Smurf2 to ubiquitinate and degrade RNF20, a RING-family E3 that controls histone H2B ubiquitination and genome stability, has been implicated for the tumor suppressive role of Smurf2." (PMID 24485087, 2014). "Our study suggests that among widely-used TNBC cell lines, MDA-MB-231 cells are unique with regard to Smurf2 regulation and perhaps its role in tumor progression." (PMID 24485087, 2014). "SMURF2 is shown to be involved in regulation of neuronal and cell polarity, induction of cellular senescence, and tumor suppression, suggesting its potential role in cellular aging." (PMID 24478790, 2013). "The expression pattern of RNF11 in human primary tumours is interesting when compared to Smurf2 in that head and neck tumours including oesophageal SCC samples expressed RNF11 in 63% of the surveyed cases." (PMID 14562029, 2003). "The interactions of SMURF1 and SMURF2 with TGF-β/BMP pathway regulators indicate that these genes may play dual roles in both tumor-suppressive and oncogenic mechanisms, depending on the cellular context." (PMID 41752056, 2026). "In addition, by utilizing the HPA database, we have also discovered that the protein expression level of SMURF2 exhibited a marked increase in the tumor group as compared to the normal group." (PMID 38698292, 2025). "Here, we identified that the upregulation of Smurf2 functions as a tumour suppressor in TNBC." (PMID 39871432, 2025). "We found that high expression of Smurf2 resulted in reduced tumour volume and weight." (PMID 39871432, 2025). "Moreover, western blotting revealed that, compared to the control group, RPL35A protein was significantly decreased in tumours with upregulation of Smurf2." (PMID 39871432, 2025). "This suggests that enhancing SMURF2 activity could be a viable strategy to mitigate the effects of HIF1α-driven tumor progression, particularly in hypoxia-adapted tumors." (PMID 39697237, 2024). "Consequently, overexpression of SMURF2 enhances the sensitivity of tumor cells to ferroptosis induced by sulfasalazine (SAS)." (PMID 39697237, 2024). "As a tumor suppressor, SMURF2 can inhibit cell proliferation and prevent malignant transformation." (PMID 39697237, 2024). "Targets Smurf2 and inactivates retinoblastoma that involves in tumor suppression." (PMID 39744000, 2024). "This interaction suggests that SMURF2 could play a role in destabilizing HIF1α-related signaling, thereby indirectly affecting the tumor’s adaptation to hypoxic conditions." (PMID 39697237, 2024). "By focusing on the HIF1α-SMURF2 axis, researchers and clinicians could develop innovative strategies to combat tumor progression, improve treatment responses, and potentially overcome resistance in cancer therapy." (PMID 39697237, 2024). "Exploring SMURF2’s role in this context could reveal novel strategies for targeting tumor angiogenesis and improving therapeutic outcomes." (PMID 39697237, 2024). "SMURF2’s tumor suppressor properties extend beyond HIF1α regulation." (PMID 39697237, 2024). "This variability presents therapeutic opportunities, where targeting SMURF2 could either amplify its tumor-suppressive functions or mitigate its tumor-promoting activities." (PMID 39697237, 2024).
tumor (continued). "Investigating SMURF2’s interactions within this pathway could provide valuable insights into the mechanisms driving tumor invasion and metastasis, offering potential targets for therapeutic intervention." (PMID 39697237, 2024). "SMURF2’s regulation of protein stability could impact HIF1α activity and, consequently, its role in promoting tumor progression and metastasis." (PMID 39697237, 2024). "Therefore, the role and regulation of Smurf1 or Smurf2 are emerging critical topics in tumor biology research." (PMID 37537194, 2023). "This study revealed that the manipulation of ID2 via SMURF2 may control tumor progression and contribute to the development of novel targeted antitumor drugs." (PMID 37497010, 2023). "Taken together, these findings highlight a tumor-suppressive role for Smurf1 and Smurf2 in Shh-MB." (PMID 37537194, 2023). "We identified the tumor-suppressing role of SMURF2 in LUAD, but whether SMURF1 has the same effect needs to be further studied." (PMID 37497010, 2023). "Depletion of SMURF2 resulted in a significant increase in xenograft tumor development and volume." (PMID 37497010, 2023). "The potential tumor suppression mechanisms of SMURF2 in LUAD were investigated." (PMID 37497010, 2023). "Notably, negative correlations between GAB1 and Smurf1 or Smurf2 were observed, confirming the downregulated expression of Smurf1 and Smurf2 in Shh-MB and supporting a tumor-suppressive role of Smurf1 and Smurf2 during Shh-MB progression." (PMID 37537194, 2023). "Mechanistically, the decrease in the nuclear pool of Smurf2 and increase in its cytoplasmic abundance could change the Smurf2’s access to its protein substrates, which include both tumor suppressor and oncogenes." (PMID 35509688, 2022). "Although previous studies have indicated that Smurf2 plays some roles in cell proliferation and invasion, reports of whether Smurf2 acts as a tumor-suppressor or tumor-promoter are varied." (PMID 35361871, 2022). "The clinical data indicated that Smurf2 might play a tumor-suppressive role in CRC; therefore, in vitro experiments were performed to elucidate the molecular mechanisms by which Smurf2 regulates the behavior of CRC cells." (PMID 35361871, 2022). "This is the first investigation of a protein from the UPS family connected to a targeting component, and despite previous reports of tumor-enhancing traits of the Smurf2 protein, our findings clearly demonstrate the tumor-suppressive activity of the Smurf2 component." (PMID 36612252, 2022). "Through regulation of a large number of proteins in multiple cellular compartments, and as part of the HECT family, with its intrinsic catalytic activity, Smurf2 functions as a tumor suppressor as described, and as such was chosen as the killing component of the chimeric proteins in this study." (PMID 36612252, 2022). "Therefore, Smurf2 plays different tumor-promoting or anti-tumor effects in different cancers which require further study." (PMID 35509688, 2022). "Mechanistically, the anti-tumor activity of Androg essentially relied on the reduction in host cell proteins, which are associated with ubiquitin-mediated proteolysis pathways, particularly HERC4 and SMURF2." (PMID 34202736, 2021). "However, Smurf2 can either act as tumor promoter or suppressor, depending on various factors such as tumor stage and type, amongst others." (PMID 34577077, 2021). "The tumor suppressor activity of Smurf2 is related to the ability of Smurf2 to induce cell senescence when telomers are shortened, thus avoiding the accumulation of mutations by degrading Id1 (Inhibitor of DNA binding 1), which leads to the expression of p16 that is the ultimate senescence inducer." (PMID 34577077, 2021). "It would be intriguing to explore whether Smurf2 plays a tumor suppressive role alternatively to VHL in this context through targeting HIF-α." (PMID 34611473, 2021). "TGF-β signaling is a bridge between the ubiquitination of Smurf2 and tumor cell activities." (PMID 33718111, 2020).
tumor (continued). "Also, SMURF2 and Mdm2 that acts as a potent tumor suppressor in normal cells, can behave as an oncogene in established tumors." (PMID 33260674, 2020). "The results suggested that CUEDC1 might efficiently inhibit tumor metastasis through suppressing EMT by the regulation of the Smurf2/TβRI/Smad signaling pathway." (PMID 33099540, 2020). "Interestingly, a slower turnover rate of cytoplasmic SMURF2 was also observed in untransformed MCF10A cells, though a ratio between the cytoplasmic and nuclear pools of SMURF2 in these cells was considerably lower in comparison to tumor cells." (PMID 31003445, 2019). "Recently, we uncovered an additional mechanism by which SMURF2 could exert its tumor suppressor functions." (PMID 31003445, 2019). "However, Huang et al19 revealed that MIR503HG promoted tumour cell proliferation and growth in vitro and in vivo through regulating miR‐503/Smurf2/TGFBR axis in anaplastic large‐cell lymphoma." (PMID 31062436, 2019). "Importantly, Smurf2 and CNKSR2 expression has been associated with features of tumor aggressivity, ER and PR negativity and HER2 overexpression." (PMID 29534682, 2018). "Furthermore, ours and other studies show that subcellular biodistribution of Smurf2 is prominently altered in cancer vs. normal cells, with a notable accumulation/sequestration of Smurf2 in the cytoplasm of tumor cells." (PMID 30116722, 2018). "The downregulation of Smurf2 protein observed in TNBC may contribute to enhanced TGF-β signaling leading to tumor invasion, epithelial-mesenchymal transition and metastasis." (PMID 24485087, 2014). "This correlation of Smurf2 with CNKSR2 may explain the role of Smurf2 in proliferation and invasiveness of tumor cells." (PMID 25191523, 2014). "Recent studies suggest that Smurf2 functions as a tumor suppressor in mice." (PMID 24485087, 2014). "Indeed we have shown that out of the endothelial enriched genes, Smurf2, Hex-B, Atf1, and Nras, plus Rrm2, which has known roles in tumour biology, that depletion of Rrm2, Atf1 and Hex-B have anti-angiogenic consequences in ex vivo mouse aortic ring assays." (PMID 23056178, 2012). "Together, these data suggest that Smurf2 promotes tumor cell migration and invasion." (PMID 20825672, 2010). "Moreover, further studies should assess whether Smurf2 overexpression inhibits tumor growth through regulation of CASC3 in vivo." (PMID 40978141, 2025). "However, levels of SMURF2 were detected to be downregulated in the tumor tissues." (PMID 37568787, 2023). "In normal conditions, Smurf2 is responsible for maintaining genome stability, thus acting as a tumor suppressor by regulating, among other substrates, the TFG-β pathway (Transforming Growth Factor beta) that is implicated in tumor suppression and embryonic development processes." (PMID 34577077, 2021). "If this finding is corroborated in tumor cell models it might be highly pertinent to the ability of Smurf2 to interfere with carcinogenesis, as EZH2 was documented as a pro-oncogenic factor involved in neoplastic transformation, cancer cell stemness, metastases and immune evasion." (PMID 30116722, 2018). "The possible pro-oncogenic functions of Smurf2 in genetically-compromised tumor cells could be related to the reported ability of Smurf2 to interfere with the RAS, Wnt/β-catenin, and EGFR-mediated signaling pathways, three central modules in cancer progression and chemoresistance." (PMID 30116722, 2018). "Moreover, Smurf2 is directly suppressed by miR-503, thereby promoting tumor progression." (PMID 29758012, 2018). "Here, we identify the E3 ubiquitin ligase SMURF2 as a key nuclear regulator that restricts NRF2 activity and attenuates tumor progression." (PMID 41926909, 2026). "We further investigated the relationship between SMURF2 and SLC31A1 expression in tumor tissues from 10 OSCC patients." (PMID 40719074, 2025).
tumor (continued). "In some cancers, SMURF2 stabilizes proteins like KRAS and EGFR and activates pathways such as Wnt/β-catenin, contributing to tumor progression and resistance to therapy." (PMID 39697237, 2024). "Next, the expression of Smurf2 in HCC tissues, adjacent non-tumor liver tissues, and human HCC cell lines, was detected by western blot analysis." (PMID 35509688, 2022). "In our research, Smurf2 mainly plays a tumor suppressor effect in HCC, which is different from the tumor-promoting effect in some other cancers." (PMID 35509688, 2022). "Here, we report SMURF2, the HECT-type E3 ubiquitin ligase and suggested tumor suppressor, as a novel regulator of KAP1." (PMID 35406379, 2022). "The expression of Smurf2 in human HCC and adjacent non-tumor liver specimens was detected using tissue microarray studies from 220 HCC patients who underwent curative resection." (PMID 35509688, 2022). "SMURF2, a significant partner for TRAF4, exhibits multifaceted functions serving as both tumor promoter and suppressor and is involved in apoptosis, metastasis, senescence, and genomic stability." (PMID 35864174, 2022). "According to our results, SMURF2 directly binds to and decreases the stability of HER2, which is consistent with SMURF2’s tumor suppressive functions." (PMID 35864174, 2022). "Smurf2 overexpression inhibited the expression of snail, slug, and Twist1/2, which indicated that Smurf2 affected EMT of HCC and inhibited tumor progression by affecting EMT inducible transcription factors." (PMID 35509688, 2022). "To assess the effects of Smurf2 on tumor cell proliferation in vitro, we performed CCK-8 assays following the knockdown of Smurf2 using siRNAs." (PMID 35361871, 2022). "Many ligases like Smurf1, Smurf2, Nedd4-2, arkadia, etc., are involved in TGF-β signaling, but E3 ligase ectodermin is an enzyme whose altered expression can lead to tumor formation via inhibiting Smad4, thereby blocking the TGF-β pathway." (PMID 34769401, 2021). "The dissociated AIMP2 translocated to the nucleus and bound to Smad ubiquitin regulatory factor 2 (Smurf2), thereby enhancing the ubiquitination of FBP and inhibiting tumor formation." (PMID 32709848, 2020). "Overall, our work illuminates the potential mechanism of how the tumor suppressive E3 ubiquitin ligase SMURF2 could be inactivated in human cancer through the alterations in its subcellular localization, and connects the altered biodistribution of SMURF2 to human carcinogenesis." (PMID 31003445, 2019). "MIR503HG-induced proliferation was mediated by the induction of microRNA-503 (miR-503) and suppression of Smurf2, resulting in stabilization of the tumor growth factor-β receptor (TGFBR) and enhanced tumor cell growth." (PMID 29758012, 2018). "We found that Smurf2, a HECT type E3 ubiquitin ligase and recently suggested tumor suppressor, functions as a physiological regulator of A‐lamins, in particular of lamin A and its disease‐associated mutant form progerin, fine‐tuning their expression levels." (PMID 29405587, 2018). "In contrast, Imamura's group showed that Smurf2 knockdown in MDA-MB-231 cells enhances cell migration in vitro and bone metastasis in vivo, implying that under these circumstances Smurf2 is a tumor suppressor." (PMID 30116722, 2018). "In the case of adrenocortical carcinoma (ACC), the expression of SMURF2 was significantly lower in tumor samples as compared to normal tissue." (PMID 38698292, 2025). "Among the multiple tumor types, LUAD exhibited high SMURF2 expression." (PMID 37497010, 2023). "The E3 ubiquitin ligase SMURF2 is another NEDD4 family member that plays a controversial role in cancer biology; some studies have indicated a tumor suppressive role of SMURF2, whereas others reported its tumor-promoting role." (PMID 36918822, 2023). "Smurf2 is known to regulate RNF20, whose high expression strongly correlates with tumor formation." (PMID 36612252, 2022).
tumor (continued). "In this study, we found that Smurf2, a HECT-type E3 ubiquitin ligase, is a tumor suppressor of HCC." (PMID 35509688, 2022). "Interestingly, loss of Smurf2 function may have differential effects in nontumor vs. tumor cells." (PMID 35710591, 2022). "However, this Smurf2 function can be reversed by phosphorylation events, leading to the promotion of TGF-β signaling-mediated tumor progression." (PMID 33718111, 2020). "SMURF2 has a key role in Ubiquitin E3 ligase regulation of the TGF-beta pathway and was found significantly down-regulated (four-fold, P = 1.5e-246 by Wald test in DESeq2 package) in SW620 metastatic cells relative to SW480 primary tumor cells." (PMID 29479369, 2018). "Cooperatively, these studies suggest that in immortalized and established cancer cell models Smurf2 operates as an oncogene rather than a tumor suppressor." (PMID 30116722, 2018). "Our ongoing study for undefined tumor-suppressive targets of Smurf2 is expected to provide not only novel insight into the biology of TNBC but also candidates for therapeutic targets against this aggressive cancer." (PMID 24485087, 2014). "The SMAD-specific E3 ubiquitin protein ligase 2 (SMURF2) has emerged as a critical regulator in cancer biology, modulating the stability of Hypoxia-Inducible Factor 1-alpha (HIF1α) and influencing a network of hypoxia-driven pathways within the tumor microenvironment (TME)." (PMID 39697237, 2024). "Thus, targeting this pathway could inhibit tumor growth and progression, suggesting that therapies combining CDK4/6 inhibitors with agents that modulate SMURF2 activity could enhance anti-cancer efficacy." (PMID 39697237, 2024). "Interestingly, in normal cells, SMURF2 has a negative impact on TRIM28 expression, whereas SMURF2 stabilizes TRIM28 in tumor cells." (PMID 39100077, 2024). "Given SMURF2’s role in protein ubiquitination, it may intersect with these pathways by influencing HIF1 stability and activity, thus impacting the Warburg effect and its contributions to tumor growth." (PMID 39697237, 2024). "Accordingly, we speculated that the negative control of cell growth by SMURF2 may explain its tumor-suppressive effect on LUAD." (PMID 37497010, 2023). "For example, SMURF2 governs the chromatin organization, dynamics, and genome integrity by controlling the proteasomal degradation or the protein stability of its substrates including RNF20 or DNA topoisomerase IIa41,43, which in turn regulate tumorigenesis and tumor progression." (PMID 35017630, 2022). "In addition, Nur77 positively regulated the interaction of Smurf2 and ID1 in splenic tumor tissues." (PMID 33990575, 2021). "However, some studies have documented evidence that Smurf2 functions as a tumor promoter rather than a tumor suppressor under some specific circumstances." (PMID 32733916, 2020). "However, results obtained in established cancer cell models argue that Smurf2 has a dual role and under some circumstances acts as an oncogene rather than a tumor suppressor." (PMID 30116722, 2018). "Interestingly, the evidence also showed that despite that SMURF2 operates in normal cells as a potent tumor suppressive barrier, in established tumors SMURF2 could switch a role and act as an oncogene rather than a tumor suppressor." (PMID 31003445, 2019). "It will be interesting to investigate whether some tumor suppressive functions of SMURF2 could be related to its negative effects on RUNX2 and whether AKT-mediated degradation of SMURF2 can occur in tumors, explaining the high levels of RUNX2 in certain types of cancer." (PMID 26204939, 2015). "Interestingly, while in the examined untransformed cells, SMURF2 mostly exerted a negative impact on KAP1 expression, a phenomenon that was also monitored in certain Smurf2-ablated mouse tissues, in tumor cells SMURF2 stabilized KAP1." (PMID 35406379, 2022).
tumor (continued). "Our findings show that SMURF2, a ubiquitously-expressed HECT-type E3 ubiquitin ligase with suggested anticancer activities, is capable to directly bind, ubiquitinate, and regulate KAP1 expression levels in non-cancerous and tumor cells and tissues." (PMID 35406379, 2022).